MAPK6P4 (mitogen-activated protein kinase 6 pseudogene 4)
Synonyms: Erk3ps4; formerly MAPK6PS4
Gene: Processed pseudogene on chromosome 8 (46,972,476 to 46,974,617, reverse strand). Ensembl gene ENSG00000215179.
Diseases named in the same sentence as MAPK6P4 in open-access papers:
MAPK6P4 is named in the same sentence as 2 diseases in open-access papers, as found by Europe PMC text mining. Sharing a sentence is not in itself a finding about the gene and the disease. The quoted sentences say what the papers report.
glioblastoma (1 paper, 2023). The most malignant astrocytic tumor (WHO grade IV). "The pseudogene MAPK6P4 encodes a functional peptide, which phosphorylates KLF15 at the S238 site, enhancing KLF15 protein stability and nuclear entry to promote vascular mimicry in glioblastoma." (PMID 37853052, 2023).
glioma (1 paper, 2023). A benign or malignant brain and spinal cord tumor that arises from glial cells (astrocytes, oligodendrocytes, ependymal cells). "MAPK6P4 expression was significantly higher in glioma tissues than in normal brain tissues, especially in high-grade glioma tissues." (PMID 37853052, 2023). "This research reveals a new molecular mechanism by which the pseudogene MAPK6P4 regulates VM development in GBM, and also provides new targets for the treatment of glioma in the future." (PMID 37853052, 2023).